GZMB (granzyme B)
Diseases named in the same sentence as GZMB in open-access papers (continued):
Sharing a sentence is not in itself a finding about the gene and the disease.
cancer (continued). "Herein, we report a new chemiluminescent probe to image in situ the granzyme B‐mediated killing activity of NK cells against cancer cells." (PMID 33300671, 2021). "Activated NK cells overexpress CD69, Fas ligand, and TRAIL on their surface, and secrete perforin and granzyme B to kill cancer cells." (PMID 34638944, 2021). "Within the NK cell, granzyme B is polarized toward the cancer cell, then secreted into the synaptic cleft in the form of secretory lysosomes; these migrate into the cancer cell." (PMID 34452238, 2021). "As a possible mechanism for V-aCD3 induced T-cell killing of cancer cells, we investigated the cytotoxic potential of V-aCD3 in the presence of concanamycin A (inhibitor of the granzyme b/perforin death pathway), anti-FASL or anti-TRAIL." (PMID 33824272, 2021). "GZMB is a serine protease and a pro-inflammatory molecule that promotes the progression of inflammatory diseases and cancers." (PMID 34837692, 2021). "NK cell activation further induces the release of perforins, which attach to the cancer cell membrane and open pores on its surface, allowing the diffusion of granzyme B proteins and inducing cell apoptosis." (PMID 33440866, 2021). "TGF-β suppresses granzyme B expressions in cytotoxic T cells, thus reducing their cell-killing potential and impairing their anti-cancer activity." (PMID 34234778, 2021). "The anti-cancer proteins such as granzyme-B, saporin and cytochrome-C are used as smart approach for cancer protein therapy." (PMID 33562376, 2021). "In the recent years, GzmB has been extensively studied as an immunotoxin in relation to targeted cancer therapy." (PMID 34529743, 2021). "NK cells circulate in a pre-primed state full of effector molecules, such as granzyme B and perforin, and have a natural ability to kill cancer cells." (PMID 32477340, 2020). "CTL cytotoxic function is elicited by IFN-γ and granzyme B (GzmB) production and can be affected by cancer cells." (PMID 31940491, 2020). "Recently granzyme B has been extensively studied for its role in the adaptive immune response in the context of cancer immunotherapy." (PMID 32646038, 2020). "Treatment with ipilmumab and other ICIs increase the cancer cell recognition of lymphocytes and their release of cytotoxic degranulation markers perforin and granzyme B." (PMID 33096896, 2020). "Despite GZMB’s traditional role in inducing caspase-dependent apoptosis by CTL and its association with a good prognosis, several studies have shown other cancer-promoting functions." (PMID 32764784, 2020). "Granzyme B imaging using the novel PET tracer GZP has provided a promising avenue for imaging the adaptive immune response in cancer patients treated with immunotherapy." (PMID 32646038, 2020). "Perforin is found in the granules of CD8+ cytotoxic T cells and is centrally involved in anti-cancer immune function whereby perforin binds to the cell membrane of target cells, forming a pore allowing for granzyme B injection and killing of the target cell." (PMID 33344239, 2020). "Granzyme B (GrB) is an essential cytotoxic effector in cancer immunotherapy as it can be a potential biomarker to predict the efficacy of immunotherapies including checkpoint inhibitors." (PMID 31903110, 2020). "Mechanistically, the resistance of hypoxic cancer cells to NK-mediated killing is related to selective degradation of NK-derived granzyme B in autophagosomes in target cells." (PMID 33260925, 2020). "Target cell lysis correlated with T-cell activation and secretion of granzyme B induced by the crosslinking through FOLR1-positive cancer cells as it was recently shown for CEA TCB2." (PMID 32581215, 2020). "Serpin B9 (protease inhibitor 9; PI-9) specifically targets the proteolytic activity of GZMB and diverse studies have reported increased intracellular expression of this serpin in a broad subset of human cancers." (PMID 32466293, 2020).
cancer (continued). "Protein drugs with intracellular targets, such as granzyme B (GrB), represent an interesting class of enzymes that have demonstrated high antiproliferative activity in various cancer cells." (PMID 30943985, 2019). "Granzyme B was delivered to CD44-overexpressing cancer cells on the self-assembled hyaluronic acid-epigallocatechin gallate conjugates, functionalized with linear polyethyleneimine (PEI)." (PMID 30943985, 2019). "Our data suggest that these CD4+ T cells can kill cancer cells directly via granzyme B-mediated cytotoxicity." (PMID 31362778, 2019). "The granzyme B expression within the TAI cells underlines this and is consistent with previous work showing that CD39 expression is a marker for cancer-related CD8+ T cells in the TME." (PMID 31412943, 2019). "CD4+ T cells can eliminate cancer cells directly in a perforin/granzyme B-dependent manner or indirectly via myeloid cells and/or NK cells." (PMID 31362778, 2019). "Previous studies have shown that SERPINB9 directly inhibits granzyme B, a major effector of CD+ 8 T cell cytotoxicity, and leads to resistance to cytolytic T cell killing in cancer cells, making it a plausible candidate." (PMID 31483286, 2019). "Serpinb9 was critical in enhancing the vulnerability of Ifnar1-KO cancer cells in our study, consistent with its known role as an inhibitor of granzyme B, an important mediator of T and NK cytoxicity, including killing of cancer cells." (PMID 31483286, 2019). "Inspired by the CTL-mediated mechanism, we conceived a granzyme B delivery system that mimics the functionality of CTLs to deliver GrB and kill target cancer cells." (PMID 31695790, 2019). "T cells directly kill cancer-cells via the Granzyme B and Perforin pathway and/or indirectly through the secretion of IFN-γ or tumor-necrosis-factor-alpha (TNF-α)." (PMID 31533251, 2019). "Natural killer cells are known to act against cancer cells and perform a lytic function through granzyme B and perforin release." (PMID 30875953, 2019). "This constructed nanosystem was then loaded with granzyme B, which has high antiproliferative activity in cancer cells." (PMID 30943985, 2019). "The Perforin and Granzyme B are cytoplasmic granules which are produced by activated NK cells against target cancer cells." (PMID 31870124, 2019). "In vitro, expanded NK cells were highly cytotoxic against cancer cells, displaying increased perforin and granzyme B accumulation." (PMID 31277710, 2019). "They do so by infiltrating the tumor site and releasing proteins that destroy the cancer cell membrane (Perforin), and release enzymes that lead to cancer cell apoptosis (Granzyme B)." (PMID 35847834, 2018). "For instance, IFN-γ and Granzyme B have been described as potent effector molecules of the anti-cancer defense that can inhibit metastasis." (PMID 29682184, 2018). "Researchers have developed novel nanogels based on self-assembly of hyaluronic acid-epigallocatechin gallate conjugates, linear polyethylenimine and Granzyme B for the intracellular delivery of the cytotoxic protein Granzyme B for cancer therapy." (PMID 30424010, 2018). "Inhibition of WEE1 kinase sensitized human cancer cells to both direct granzyme B-dependent haNK killing and ADCC when combined with the IgG1 mAb Avelumab." (PMID 29925431, 2018). "MAIT cells have antiproliferative effects in a cancer cell line in a cell–cell contact-dependent manner and have cytolytic activity against the cancer cell line most likely via degranulation of granzyme B and perforin." (PMID 29250077, 2017). "It is reported that there is significantly reduced granzyme B production by CD8+ T cells from cancer tissue obtained by lung resection surgery when compared to non-cancer tissue." (PMID 28099147, 2017). "Two enzymes, which have been tested to various extents for their specific cytotoxic activity in a range of cancer types, in cell culture and/or xenograft, are granzyme B (a serine protease) and angiogenin (human RNase A analogue)." (PMID 28536352, 2017).
cancer (continued). "Through a perforin-delivered intracellular granzyme B system, cancer cells can be disrupted by granzyme B-mediated cellular toxicity via different pathways, which subsequently results in cancer cell damage toward immunological cell death." (PMID 28143527, 2017). "Cut-point analysis by maximally selected log-rank statistics yielded threshold values for each chemokine and Granzyme B, based on stratification for cancer-specific survival." (PMID 29163806, 2017). "And there was significantly reduced granzyme B production by CD8+ T cells from cancer tissue when compared to non-cancer tissue." (PMID 28099147, 2017). "Recently, a new population of granzyme B (GrB)-producing B cells was identified, which was proved to be involved in cancer and infectious diseases." (PMID 28713386, 2017). "Killing by FasL occurred slowly, requiring transient, often multiple NK-cancer cell conjugations that gradually activated caspase-8, while lytic granule triggered rapid cytotoxicity by a switch-like induction of granzyme-B upon a single, prolonged conjugation." (PMID 27323411, 2016). "The cytoplasmic protease inhibitor serpin PI-9 can directly block the enzymatic activity of granzyme B that is eventually delivered into the cytosol of cancer cells through a cytolytic synapse as formed by T cells." (PMID 26510188, 2015). "SERPINB9 is a human proteinase inhibitor expressed in certain normal cell types and cancer cells of different origin and can protect the cancer cells from granzyme B (GrB)-mediated apoptosis." (PMID 25133526, 2014). "Percentage of granzyme B positive NK cells was at high levels in both the NK cells of the patients with cancer and the healthy controls." (PMID 24138752, 2013). "MUC1 glycoproteins carrying poly-N-acetyllactosamine attenuated the interaction of the cancer cells with NK cells, resulting in decreased secretion of granzyme B by the NK cells." (PMID 23165940, 2013). "Granzyme B ELISPOT assay was applied to monitoring immune responses in cancer patients in several publications." (PMID 24710418, 2012). "The αβ TCR in CD8+ CTL can recognize MHC class I-peptide complexes on cancer cells and destroy cancer cells through effector molecules such as granzyme B and perforin." (PMID 21922022, 2011). "The results indicated that in most CIN lesions only a minority of CTLs are activated, whereas in some carcinomas a massive infiltration of activated, i.e. granzyme B-positive, CTLs were observed." (PMID 9374383, 1997). "Additionally, other studies also indicated that Tregs can express both granzyme B and perforin, as crucial mechanisms for their suppressive functions in autoimmune responses and cancer." (PMID 41596443, 2026). "Coculture killing assay showed ASPG-OE CAR-T cells exhibited increased killing efficacy against ASNS-OE cancer cells by enhancing the expression of granzyme B, interferon gamma, and tumor necrosis factor alpha, whereas ASPG-knockout (KO) CAR-T cells showed decreased cancer cell lysis efficiency." (PMID 40808257, 2025). "Additionally, serine/glycine starvation decreased the expression of interferon γ (IFNγ) and granzyme B (GzmB) in OT-1 T cell co-cultures with multiple OVA-expressing cancer cell lines." (PMID 40389477, 2025). "The complex interplay between high-risk HPVs, granzyme A, granzyme B, and MHC-I may provide insights into novel approaches for targeting HPV-associated cancers." (PMID 40006976, 2025). "Live-cell imaging of control NK cells incubated with reporter-expressing cancer cells revealed that the dominant mechanism of killing depends on perforin/granzyme B. However, in the presence of NH4Cl, this mechanism was severely impaired even at low concentrations of NH4Cl." (PMID 40163355, 2025). "Notably, cancer cells undergoing actin cytoskeleton remodeling exhibited reduced levels of NK cell–delivered granzyme B, suggesting a potential impairment of NK cell cytotoxic activation." (PMID 40763024, 2025).
cancer (continued). "Finally, interferon (IFN)-responsive cancer cells, GzmB+ Tc, as well as C1q+ TAMs increase over the course of the 4-week time-course." (PMID 41280683, 2025). "Additionally, GzmB expression and cytotoxic activity against autologous cancer cells were more pronounced in the WIOG group than in the WIO group." (PMID 41280919, 2025). "This metabolic challenge suppresses the T cells' ability to secrete cytotoxic molecules like perforin and granzyme B, exacerbating their dysfunction and highlighting the pivotal role of glutamine in sustaining mitochondrial health and T cell efficacy in cancer." (PMID 40546111, 2025). "However, one of the challenges of using GZMB in cancer therapy is its inactivation by Serpin B9 (PI-9), a natural inhibitor of GZMB that is often overexpressed in cancer cells." (PMID 40766321, 2025). "Notably, NK-exos exhibit strong therapeutic effects and precise targeting through cytotoxic proteins (e.g., granzyme B and perforin), effectively killing tumors in various cancers." (PMID 40076856, 2025). "Furthermore, in all three post-PD-L1-CRT tissue samples, we confirmed that CXCL13 + CD8+ lymphocytes expressed GZMB and directly interacted with cancer cells at the single-cell resolution." (PMID 40670667, 2025). "GZMB also has potential as a biomarker for monitoring immune responses in cancer therapy." (PMID 40766321, 2025). "In addition, this study also showed that cancer-immune interactions with B cells and granzyme B+ T cells were also predictors of response to immunotherapy." (PMID 38793063, 2024). "CD8+ T lymphocytes could directly destroy cancer cells by releasing cytotoxic granules, such as granzyme B and cytokines, such as IFN‐γ and TNF‐α." (PMID 39267250, 2024). "Moreover, human cancer cell lines stably expressing Sb9 demonstrate a heightened ability to resist apoptosis triggered by both granzyme A or GzmB and Fas/Fas ligand pathway." (PMID 38966643, 2024). "Moreover, granzyme B (GrB) is constitutively expressed in human pDCs, but its production and release are further induced by the cytokines abundant in cancer tissues." (PMID 39020402, 2024). "NK cell activation can trigger apoptosis in cancer cells by several pathways, including the release of cytotoxic granules containing pore-forming perforin protein and effector serine proteases such as granzyme B." (PMID 39619199, 2024). "IL-18 can also form a positive loop with interferon-γ (IFN-γ), which exerts a series of immune activities for cancer suppression, including the activation of cytotoxic T lymphocytes (CTLs), the production of granzyme B, and the inhibition of immunosuppressive cytokines." (PMID 39398428, 2024). "There is evidence suggesting that BRAF and MEK inhibition induces CD4 and CD8 T lymphocytes, boosting their cytotoxicity against cancer cells, which is evident by elevated granzyme B and perforin levels, and an elevated expression of cytotoxic T-lymphocyte-associated protein-4 (CTLA-4)." (PMID 38731852, 2024). "However, when PD-L1 is expressed in cancer cells and interacts with PD-1 receptor in immune cells, it can inhibit the immune response, leading to a reduction in perforin and granzyme B expression and secretion." (PMID 39375538, 2024). "Many apoptotic proteins, such as granzyme B (GrB), have been investigated for cancer therapy." (PMID 37888375, 2023). "Immune checkpoint inhibitors (ICIs) act specifically to block CTLA4 and PD-1, so we compared GzmA and GzmB expression in CD57+ CD4+ T cells in blood obtained from cancer patients before and after treatment with anti-CTLA4/PD-1 (ipilimumab/nivolumab) combination checkpoint inhibitor therapy." (PMID 37161048, 2023). "CD8+ cells infiltrating cancer-cell islets featured higher expression of proteins related to effector function (GZMB, CD127), T-cell co-stimulation and co-inhibition (PD-1, LAG3, 4-1BB, GITR, STING, B7-H3), and other non-T-cell co-inhibitory proteins (PD-L1, PD-L2), IDO1, and Ki-67." (PMID 38044986, 2023).
cancer (continued). "However, our study supports that Cxcr3 is critical for immunotherapy durability through maintaining peripheral GzmB + Klrg1 + effector T cells deemed critical for mitigating cancer cell dissemination." (PMID 36472588, 2023). "The functional potential of the T-cell anti-cancer response was then assessed according to the production of IFN-γ, TNF-α, perforin, and Granzyme B. Our findings indicated that PD-L1 blockade by pentamidine enhanced the cytotoxic potential of T cells in all tested cancer cell lines." (PMID 37205112, 2023). "Collectively, these data support that the ICIE treatment may activate a strong antitumor immunity to kill cancer cells through a high level of GZMB secreted by CTLs." (PMID 36693842, 2023). "What was also interesting was the range of GzmB expression within the same cancer type." (PMID 35326588, 2022). "The majority of cancers showed a greater probability of survival with greater expression of GzmB." (PMID 35326588, 2022). "Pan-cancer expression analysis showed higher GzmB mRNA expression in many cancers such as cholangiocarcinoma, glioblastoma multiforme, head and neck squamous cell carcinoma, kidney renal clear cell carcinoma and stomach adenocarcinoma compared to normal tissues." (PMID 35326588, 2022). "Cancer cell killing by activated CD8+ T cells is potentiated by Perforin/Granzyme B activity." (PMID 36077656, 2022). "However, it also had a pleiotropic inhibitory effect on immune cells, resulting in decreased granzyme B release, making the cancer cells resistant to immune attack in the coculture condition." (PMID 36357569, 2022). "While VPS4B depletion did not perturb autophagy in human cells, in the future it would be interesting to test whether autophagy inhibition also leads to elevated granzyme B accumulation in human cancers." (PMID 35379808, 2022). "We analyzed pan-cancer expression and found that some cancers such as uveal melanoma and pancreatic adenocarcinoma have a better probability of survival when there is minor GzmB transcription compared to a large amount." (PMID 35326588, 2022). "To evaluate whether the death of cancer cells was due to stimulation of the laNK92 cells by BiKE, we measured the concentrations of cytotoxic proteins and cytokines, including Perforin, Granzyme B, IFN-γ, and TNF-α during the ADCC experiment." (PMID 36685519, 2022). "However, cancers such as lung adenocarcinoma and lung squamous cell carcinoma show low GzmB expression." (PMID 35326588, 2022). "Our results are in line with Shabsoug, who report an increase in the production of interferons and granzyme B in NK cells after treating them with different concentrations of an aqueous Nigella sativa extract; as such, K-562 cancer cell death was significantly improved." (PMID 36199754, 2022). "In order to evaluate whether the cancer cells in SCC FAK (−/−) tumors contained intracellular active GzmB, tumors were harvested and treated with probe H5 for 30 min before being analyzed by flow cytometry." (PMID 35501326, 2022). "In addition, the highly GZMB expression was connected with a good survival outcome, which is consistent with the conclusion proved in other cancers." (PMID 35957895, 2022). "In addition, NK cells release cytotoxic mediators such as granzyme B and perforin, which induce the apoptosis of cancer cells." (PMID 34638944, 2021). "As granzyme B plays an important role in mediating the apoptosis of cancer cells, we next investigated the apoptosis of cancer cells in the direct and indirect co-culture systems with CD8+ T cells at a ratio of 1:5 with or without compound 968 using the annexin V apoptosis assay." (PMID 34944392, 2021). "The cytokines secreted from Tregs, such as perforin and granzyme B, could directly kill anti-cancer immune cells, including antigen presenting cells and T effector cells." (PMID 35111682, 2021).